FOXO1 (forkhead box O1)
Diseases named in the same sentence as FOXO1 in open-access papers (continued):
Sharing a sentence is not in itself a finding about the gene and the disease.
infection (continued). "In the converse approach, the infection of islets with AdSirt6 increased mRNA and protein levels of Glut2, GK, and Pdx1 and decreased FoxO1 protein expression, indicating the presence of a causal relationship between Sirt6 and FoxO1-Pdx1-Glut2." (PMID 27457971, 2016). "The transcription factor FoxO1 sustains expression of PD-1 during chronic LCMV-Cl13 infection involving increased PKB/AKT activity." (PMID 26885856, 2016). "Western blot analysis showed that miR-9 decreased exogenous overexpressed FoxO1 protein by Ad-CA FoxO1 infection." (PMID 26593208, 2015). "It was interesting that the peak of RNA production was similar between AS1842856 treated and control infections, consistent with the notion that Foxo1 inhibition mainly accelerates the establishment of infection." (PMID 25330112, 2014). "Since de novo HIV-1 expression was required for these effects, there will of necessity be some delay between infection and Foxo1 suppression." (PMID 25330112, 2014). "The results revealed that binding of FOXO1 to the upstream promoter of Lgals9 was enhanced post-infection, suggesting that FOXO1 could directly bind to the Gal-9 promoter and suppress its transcriptional expression following T. gondii infection." (PMID 38987795, 2024). "In addition, infection with the H. pylori ΔhtrA mutant led to activation of the FOXO1 upstream regulator, another transcription factor involved in apoptosis regulation." (PMID 37193047, 2022). "The depletion of FoxO1 in germinal center B cells led to diminished somatic hypermutation and dwindled class switching, which significantly hampered a robust antibody response to infections." (PMID 36233176, 2022). "We observed an initial increase in the FoxO1 and FoxO3 levels between 1 h.p.i. and 12 h.p.i. and a slight decrease later in infection, which could be explained by the increase in miRNAs late in infection." (PMID 36016282, 2022). "Similarly, infection of pre-B cells with pre-miR-582 lentivirus inhibited phosphorylation (p-AKT) while promoted FoxO1 phosphorylation (p-FoxO1); and interfering miR-582 with anti-miR-582 lentivirus exhibited opposite effects." (PMID 35115499, 2022). "However, infections of HG-treated FOXO1 KO cells with si-TX greatly reduced the levels of apoptosis and fibrosis indicators compared with these infected with si-NC." (PMID 30962862, 2019). "In our study, we detected greater levels of Foxo1 mRNA in the TA than in the DIA at day 3 post-infection, suggesting that Foxo1 may contribute to the up-regulation of Lc3b, Gabarapl1, and Bnip3 that is seen in the TA in response to infection." (PMID 28659735, 2017). "GFP+ cells emerged earlier in the AS1842856 treated cultures, and at two days after infection, the total GFP fluorescence in the culture was enhanced by an order of magnitude, consistent with the interpretation that Foxo1 suppression assists the establishment of infection in cells." (PMID 25330112, 2014). "In addition, we detected a marked reduction in FOXO3a and FOXO1 protein expression upon infection." (PMID 41450565, 2025). "Thus, the upregulation of FOXO1 may be a mechanism to alleviate stress-induced damage on LACs in KO male mice compared to female mice in response to infection." (PMID 35844510, 2022). "However, in the case of absolute or relatively insufficient insulin levels, such as fasting or infection stress, FOXO1 may be transferred from the cytoplasm and be retained in the nucleus under the action of the Jun-N-terminal kinase (JNK) signalling pathway." (PMID 34249128, 2021). "Transcriptome data in the present study revealed a significant decrease in FoxO1 expression during infection but only a slight increase in β-catenin expression, which may be related to the up-regulation of β-catenin protein levels and the activation of Wnt/β-catenin signaling by LPS." (PMID 32509459, 2020).
infection (continued). "Such an effect was confirmed in PA infection, where PA-derived DnaK negatively regulates IL-1β production by cross-talk between JNK and PI3K/PDK1/FoxO1 pathways." (PMID 41164165, 2025). "While these population-level effects are strong, data at the single-cell level indicate that subsets of EBV-infected cells in both early infection and LCLs retain or upregulate DZ mRNA for CXCR4, FOXO1, AICDA, IL2RB, AURKC, and LMO2." (PMID 38059622, 2024). "Another transcription factor Forkhead box O1 (FOXO1), which can regulate TCF1 expression, has also been shown to be vital for sustaining the memory-like population of exhausted cells during LCMV Cl 13 infection." (PMID 34696381, 2021). "And Delpoux proposed Foxo1 has a key function in T cell differentiation and transport, thereby controlling the response of central memory CD8 T cells to infection." (PMID 33024415, 2020). "In search for the underlying mechanisms, we demonstrate reduced Bcl-6 accompanied by accumulated FoxO1 proteins in CD4+ T cells of Uba3ΔT mice, either under the circumstance of P. yoelii 17XNL infection or the iTfh cultures." (PMID 30462731, 2018). "Our results also demonstrate the down-regulation of transcription factor FOXO-1, and up-regulation of its controlling microRNA, i.e., miR-182, in CD4+ T cells isolated at day 12 post infection from Cm infected mice compared to mock infected animals." (PMID 27556515, 2016). "Upstream modifiers associated with the adaptive immune response including Tbx2, Foxo1, and the TCR rise in significance after day 5 post-infection and stay elevated to the end of the experiment." (PMID 26413862, 2015). "CCR7, Foxo1 and Foxo3a are also known transcriptional targets of Foxo1 or Foxo1 plus KLF2, and their mRNA levels remained unchanged during productive infection." (PMID 25330112, 2014). "The half-life of CD62L mRNA is long and our unpublished data indicate that CD62L persists on the resting T cell surface for several days, so further studies will be required to reveal the kinetics of Foxo1, KLF2 and CD62L mRNA suppression after infection." (PMID 25330112, 2014). "For example, FOXO1 and CNTN1 levels temporarily dropped during infection." (PMID 40760251, 2025). "Infection of the oral cell epithelium by P. gingivalis appears to promote the activation of key antiapoptotic pathways such as JAK1/STAT3, PI3K/Akt (protein kinase B), and Akt/FOXO1 signalling, as well as ATP-dependent apoptosis." (PMID 41228271, 2025). "The expression levels of FOXO1 and Gal-9 were detected using western blotting assay in the infection group with or without JNK inhibitor." (PMID 38987795, 2024). "We found that p-FOXO1 (Ser-256) levels were significantly decreased at 48 h post-infection, whereas p-FOXO1 (Ser-319) levels showed no significant change." (PMID 38127284, 2024). "Concerning the observed differences in proteins involved in phosphorylation pathways, the FOXO1 protein, which is critical for the OXPHOS pathway and energy metabolism, showed a significantly reduced phosphorylation level exclusively after infection with the 2022 MPX virus." (PMID 39466906, 2024). "Cardiomyocyte infection with AdSTUB1 did not elicit changes in FoxO1 mRNA levels as compared with AdGFP-infected cells." (PMID 33727534, 2021). "We confirmed our hypothesis that disruption of the FOXO1 SE reduced PAX3-FOXO1 at the transcript level and protein level at 24 h after sgRNA infection." (PMID 32416589, 2020). "The differential methylation of genes involved in memory T-cell responses, such as CD44, FOXO1 and FOXC1, might contribute to the inability of the host to mount responses capable of clearing infection." (PMID 27484700, 2016). "In a first step, we tested if infection with retroviruses, which overexpress phosphorylation-independent and thus constitutively active (CA) forms of STAT5 or FOXO1, might rescue FOXP3 expression in the presence of the TCR-signal and absence of TGFβ." (PMID 26815406, 2015).
infection (continued). "FOXO3 protein expression but not that of FOXO1 was significantly suppressed 3 days after its infection in keratinocytes." (PMID 25647160, 2015). "The Foxo1 inhibitor AS1842856 accelerated de novo viral gene expression and the sequella of infection, supporting the notion that HIV-1 suppression of Foxo1 activity may be a strategy to promote replication in resting CD4 T cells." (PMID 25330112, 2014). "Interestingly, FKBP1B and FOXO1 are also related to cardiac function, but contrary to TNNI3 they are increased in the LC group, suggesting their potential involvement in the long-term cardiac dysfunction instead of the acute phase of the infection." (PMID 40247373, 2025). "We first determined whether FOXO1 inhibition by AS1842856 allowed the infection of resting T cells by HIV-1, in the absence of any additional treatment." (PMID 31042779, 2019). "Thus inhibition of FOXO1, in the absence of any other cell treatment, allows infection of resting T cells by HIV-1." (PMID 31042779, 2019). "Another study regarding the Ad36 infection of hADSCs cells reported that infection might promote FA and TAG synthesis and subsequent LD formation by modulating phosphoinositide 3-kinase (PI3K)/protein kinase B (Akt)/ forkhead box O1 (FoxO1)/ PPARγ signaling pathway." (PMID 35883666, 2022). "Also the expression of transcription factors was significantly modified by HHV-6A/6B infection, with an early increase of ATF3, JUN and FOXA2 by both species, whereas HHV-6A specifically induced a 15-fold decrease of POU2AF1, and HHV-6B an increase of FOXO1 and a decrease of ESR1." (PMID 29163428, 2017). "Importantly, neither the infection status nor phenotypic and functional markers (e.g., CD4, Ki-67, CD169, and FoxO1) were considered in defining CNs; therefore, the microenvironment was defined using only the spatial phenotypic patterns." (PMID 35447093, 2022). "Whereas infection of NRVMs with AdXBP1s resulted in increases in SKP2 mRNA, SKP2 knockdown using SKP2-specific siRNA (siSKP2) did not relieve Xbp1s-dependent FoxO1 protein degradation." (PMID 33727534, 2021).
metabolic disorders (51 papers, 2016 to 2026). "Cell proliferation, apoptosis, autophagy, oxidative stress and metabolic disorders underlie many diseases, and forkhead box transcription factor 1 (FOXO1) plays a key role in these physiological and pathological processes." (PMID 36964488, 2023). "Abnormal expression of Foxo1 protein is associated with metabolic disorders and the use of Foxo1 inhibitors resulted in the improvement of glucose metabolism." (PMID 34069853, 2021). "Dysregulation of FOXO1 has been previously associated with metabolic disease and muscle atrophy." (PMID 38769106, 2024). "This activation process activates Forkhead box protein O1 (FoxO1), which is a significant contributor to metabolic diseases." (PMID 40746564, 2025). "The excess ROS promotes the nuclear translocation of FoxO1, which in turn upregulates AgRP expression, ultimately resulting in metabolic disorders." (PMID 41037185, 2025). "Although some essential modulatory effects of FOXO1 on leukocytes have been reported in metabolic diseases and bacterial infection, its role in TBI and the regulation of neutrophils remains poorly understood." (PMID 38556884, 2024). "Previous studies by us and others have demonstrated a marked increase in FOXO1 expression in the context of metabolic disorders." (PMID 38745315, 2024). "TMAO triggers the activation of the transcription factor FoxO1, known for its pivotal role in metabolic disorders, through a PERK-dependent pathway." (PMID 38892643, 2024). "Subsequently, activated FOXO1 disrupts mitochondrial oxidative and phosphorylation activities (OXPHOS), resulting in deficient ATP synthesis and metabolic disorders." (PMID 35154571, 2022). "TMAO binds to PERK at physiologically relevant concentrations, selectively activates the PERK branch of the unfolded protein response, and induces the transcription factor Forkhead Box O1 (FoxO1) in the liver, which is a key driver of metabolic disease." (PMID 36465656, 2022). "Specifically, at physiologically circulating levels, TMAO binds to the endoplasmic reticulum stress kinase, thus inducing the forehead transcription factor FoxO1, a key driver of metabolic disease." (PMID 34200594, 2021). "On the other hand, the involvement of the miR-27 family in metabolic disorders and in hepatic glucose metabolism was described, with it having forkhead box O1 (FOXO1) as a downstream target." (PMID 34660810, 2021). "FoxO1 transcriptionally mediates pathways responsible for many metabolic diseases that are translated by the FoxO1 gene, a member of FoxO genes belonging to the transcription factor (TF) family." (PMID 33281814, 2020). "FoxO1 is a commonly expressed member of the forkhead factor family and has long been considered to be involved in metabolic disorders, especially the lipid and glucose metabolism." (PMID 30186875, 2018). "The reconstitution of FoxO1 using IL-6-deficient mice and pharmacological treatment did not protect against metabolic disorder but prevented SMC hyperproliferation." (PMID 35896539, 2022). "Selectively silencing FOXO1 has the potential to treat metabolic disorders." (PMID 31936903, 2020). "In addition to its important regulatory roles in oncogenesis, FoxO1 also transcriptionally mediates pathways behind many metabolic diseases, including gluconeogenesis, glycogenolysis, adipogenesis, thermogenesis, and feeding behavior, which is the focus of this review article." (PMID 31936903, 2020). "This interaction selectively activates the PERK branch of the unfolded protein response, and induces the transcription factor Forkhead box protein O1 (FOXO1), a key promoter of metabolic disease, which can be prevented by interventions to reduce TMAO." (PMID 37367916, 2023). "The FoxO1/PDK4 pathway inhibits glucose utilization in skeletal muscle by regulating PDHC activity, which eventually results in metabolic diseases." (PMID 36986243, 2023).
metabolic disorders (continued). "Importantly, interactions between SIRT1, peroxisome proliferator-activated receptor gamma coactivator 1 (PPARGC1A), and FOXO1/FOXO3 indicate a strong mitochondrial and antioxidant component, aligning with their roles in metabolic disease and aging." (PMID 40664894, 2025). "Furthermore, TMAO binds and activates PKR-like endoplasmic reticulum stress kinase (PERK) at physiologically relevant concentrations and induces the transcription factor forkhead box protein O1 (FOXO1), which is the main driver of metabolic disease, in PERK-dependent signaling." (PMID 34201938, 2021).
cardiovascular diseases (17 papers, 2013 to 2025). "Altered FoxO1 expression and activity have been associated with cardiovascular diseases in diabetic subjects." (PMID 39206323, 2024). "Altered FOXO1 expression and function have been associated with cardiovascular diseases, and the important role of FOXO1 in DCM has begun to attract attention." (PMID 26956801, 2016). "Although FOXO1 has been extensively studied in cardiovascular diseases, the role of FOXO1 in AAA requires further investigation." (PMID 35990982, 2022). "Curcumin induces a beneficial form of autophagy in H2O2-exposed human vascular endothelial cells via a protective mechanism involving FOXO1, which may be a potential therapeutic avenue for the treatment of oxidative stress-related cardiovascular diseases." (PMID 28088783, 2017). "We may be able to better predict cardiovascular disorders in children by understanding the pathophysiology of the atherosclerotic diseases using a combination of clinical criteria, carotid evaluation, and epigenetic markers such as SIRT1/FOXO1." (PMID 36289866, 2022).
inflammation (12 papers, 2015 to 2026). Aberrant reaction of the microcirculation characterized by movement of fluid and leukocytes from the blood into extravascular tissues. "During endothelial inflammation, m6A modification of FOXO1, an important transcription factor, was remarkably increased." (PMID 32802173, 2020). "Combined, these data suggest involvement of autophagy-mediated degradation in pulmonary inflammation-induced muscle atrophy through mTOR inhibition and FoXO1 activation, in addition to UPS-mediated proteolysis." (PMID 29720191, 2018). "We also demonstrate that disruption of PTEN/Foxo1 signaling contributes to the inhibition of lung inflammation." (PMID 25759027, 2015). "To further elucidate the mechanism by which PTEN/Foxo1 signaling may regulate HMGB1-induced lung inflammation, we isolated alveolar macrophages in BALF from rHMGB1-instilled lungs." (PMID 25759027, 2015). "Our results highlight the importance of myeloid Foxo1 signaling as a key regulator of the NEK7/NLRP3 activation and hepatocyte necroptosis in IR stress-mediated liver inflammation." (PMID 33288903, 2021).
kidney disease (10 papers, 2016 to 2026). "Overall, MHY3200 effectively ameliorated renal inflammation by regulating the ROS/Akt/FoxO1 pathway and exerted beneficial effects on renal disorders caused by aging." (PMID 34073584, 2021). "Alternatively, in an I/R model, Foxo1 protein levels increased and phosphorylated-Foxo1 levels decreased, suggesting that FOXO1 activation may be a pathogenic component driving kidney disease." (PMID 37814337, 2023). "While we established a clear relationship between miR-9-5p and Foxo1 in LN models, the broader implications of this axis in other renal disorders remain to be explored." (PMID 40886372, 2025). "Foxo1 is a putative target of miR-486-5p based on a Targetscan prediction, with an interaction being reported in the context of kidney disease." (PMID 36303988, 2021). "We identified six common target genes associated with renal diseases, and three (HIF1A, FOXO1, KLF4) are related specifically with LN." (PMID 32085620, 2020).
neurodegenerative disease (8 papers, 2009 to 2025). A disorder of the central nervous system characterized by gradual and progressive loss of neural tissue and neurologic function. "Given the association between autophagic homeostasis and degenerative diseases, our study also focuses on the role of FOXO1 in cellular autophagy." (PMID 41013182, 2025). "More research is needed to better understand FoxO1’s role in the pathology of neurodegenerative diseases." (PMID 37941908, 2023). "FOXO1 and IRS2 play important roles in the occurrence and treatment of tumors as well as in neurodegenerative diseases, but the association between their m6A modification and aging has rarely been reported." (PMID 36012545, 2022). "Moreover, Klf9, Foxo1, and Clock, which play significant roles in neurodegenerative diseases and age-related cognitive decline, regulate downstream genes associated with neurogenesis, synaptic plasticity, and membrane potential." (PMID 41450877, 2025). "Because of FoxO1’s role in regulating brain metabolism, it may link metabolic dysfunction and neurodegenerative disease." (PMID 37941908, 2023).
bacterial infection (5 papers, 2017 to 2025). "Regarding neutrophils, a previous study has shown that FOXO1 can induce C‐X‐C motif chemokine ligand 2 and C‐X‐C motif chemokine receptor 2 in bacterial infection that is associated with enhanced neutrophil mobilization." (PMID 38556884, 2024). "During viral and bacterial infections, Foxo1 is essential for promoting differentiation of long-lived memory T cells and thus enhancing recall responses." (PMID 38409097, 2024). "FoxO signaling pathway: FoxO1 protein is expressed by a bacterial infection, strengthening the epithelial barrier of host cells and inducing the recruitment of Tregs (Regulatory T Cells) to activate the antibacterial defense." (PMID 35216171, 2022). "Moreover, FOXO1 plays a critical role in upregulating antibacterial neutrophil responses that clear bacterial infection including phagocytosis and bacterial killing." (PMID 28928749, 2017). "Therefore, we speculate that a potential pathway influencing subtype I may involve bacterial infection, leading to BANK1-FOXO1 (forkhead box O1) pathway dysregulation and lymphocyte abnormalities." (PMID 40520994, 2025).